ICAM1 (intercellular adhesion molecule 1)
Diseases named in the same sentence as ICAM1 in open-access papers (continued):
Sharing a sentence is not in itself a finding about the gene and the disease.
thyroid cancer (29 papers, 2011 to 2025). "Sparing toxicities by reducing the affinity has been demonstrated for ICAM-1 specific CAR T cells (micromolar affinity) in thyroid cancer, as well as in HER2- and EGFR-specific CAR T cells in various solid cancer models including ovarian and prostate." (PMID 38962014, 2024). "In the case of ICAM-1, there are abundant preclinical data with promising results, like the targeting of ICAM-1 using CAR-T cells in advanced thyroid cancer." (PMID 38542421, 2024). "In the groups of the TCGA cohort, both B7-H3 and ICAM-1 mRNA were highly expressed in thyroid carcinoma." (PMID 38858715, 2024). "In the present study, we explored the expression level of B7-H3 and ICAM-1 in different types of thyroid carcinoma." (PMID 38858715, 2024). "In similar xenograft models, ICAM-1 CAR T cells are also able to eliminate thyroid cancer tumors formed by patient-derived advanced thyroid cancer cells." (PMID 37237555, 2023). "Hayes and Seigel15 analyzed approximately 300 samples of normal, malignant, and metastatic tissues from various tumors, including thyroid cancer, and found overexpression of both the ICAM1 gene and ICAM-1 protein in malignant tissues." (PMID 36906717, 2023). "MiR-335-5p binds to the ICAM1 3′UTR (untranslated region) and inhibits ICAM1 expression, thereby limiting the migration, invasion, and metastasis of thyroid cancer cells." (PMID 37671167, 2023). "The first study on CAR T-cell therapy for advanced thyroid cancer revealed the development of an intercellular adhesion molecule 1 (ICAM 1)- specific CAR T-cell and its preclinical efficacy." (PMID 35936003, 2022). "It has been reported that miR-335-5p can inhibit thyroid cancer cells invasion and metastasis via targeting ICAM-1." (PMID 34362407, 2021). "Kopp and colleagues demonstrated that real microgravity induced the expression of VCAM1 and ICAM1 in thyroid cancer cells (FTC-133 cell line) during sounding rocket flight." (PMID 32344794, 2020). "Successful in vivo studies using 4-1BB/CD28 third generation CARs include an ICAM-1 CAR for a mouse model of thyroid cancer, a GPC3 CAR in a patient derived xenograft of model of HCC, and a VEGFR2 CAR against multiple tumor types in vivo." (PMID 30804938, 2019). "Previously, we have shown a significant correlation between ICAM-1 overexpression and malignancy in thyroid cancer, and have pioneered the use of ICAM-1 targeted CAR T cells as a novel treatment modality." (PMID 31337787, 2019). "Poorly differentiated thyroid carcinomas show higher ICAM-1 expression levels than well-differentiated carcinomas, supporting the thesis that ICAM-1 upregulation induces a more aggressive tumor phenotype." (PMID 30657059, 2019). "The biological significance of iCAM-1 expression in cancer remains controversial; it is elevated in gastric, breast, oral, and thyroid cancer tissues but reduced in some ovarian adenocarcinoma cell lines and primary tumors." (PMID 26230496, 2015). "The significant relevance of B7-H3 staining score with ICAM-1 staining score was observed in TCGA database and our cohort, which might open avenues for the combination therapy in advanced thyroid cancer." (PMID 38858715, 2024). "ICAM-1 expression is upregulated in patients with PTC, and correlated with aggressiveness tumour features such as BRAFV600E mutation, extra-thyroidal extension, and lymph node metastasis in thyroid cancer progression." (PMID 35871446, 2023). "Another condition reported was elevated soluble ICAM 1 found in the serum of patients with thyroid cancer, which might neutralize anti-ICAM 1-CAR T-cells in the periphery before recognizing ICAM 1+ tumor cells." (PMID 35936003, 2022). "Our trackable CAR T cell therapy targeting intercellular adhesion molecule 1 (ICAM-1) is currently being evaluated in a Phase 1 trial against advanced thyroid cancer (ATC) for safety and the feasibility of CAR T cell imaging using 68Ga-DOTATATE (ClinicalTrials.gov Identifier: NCT04420754)." (PMID 36463361, 2022).
thyroid cancer (continued). "In thyroid cancer, miR-335-5p could interfere with invasion and metastasis of tumor cells via downregulating ICAM-1." (PMID 34081622, 2021). "However, ground-based studies revealed that the expression of ICAM1 protein was lower in RPM-induced thyroid cancer cells." (PMID 32344794, 2020). "In addition, alterations of NOX4 could be associated with thyroid cancer (via activation by H-Ras oncogene) and Hashimoto's thyroiditis, in which the increased extracellular expression of this enzyme raises Intercellular Adhesion Molecule-1 (ICAM-1) expression and cytokine release." (PMID 27051079, 2016). "For example, a previous report showed the expression of ICAM-1 in thyroid carcinoma cells." (PMID 21364949, 2011). "Additionally, ICAM-1-targeted CAR-T cell therapy may offer a potential treatment option for high-grade thyroid cancer." (PMID 40299520, 2025). "In preclinical model, CAR T cells targeting ICAM1 could eliminate advanced thyroid cancer." (PMID 34408980, 2021). "T cells were transduced with the anti-ICAM-1 CAR and their cytotoxicity against the ICAM-1+ thyroid cancer cell lines was evaluated." (PMID 34258030, 2021). "This study focuses on L-selectin, ICAM-1 and LFA-1 to better understand their role in the migration of neoplastic cells seeking possible practical applications in the diagnosis and prognosis of thyroid cancer." (PMID 36906717, 2023).
inflammatory bowel disease (25 papers, 2012 to 2025). A spectrum of small and large bowel inflammatory diseases of unknown etiology. "The present study evaluated the association between G241R and K469E polymorphisms of intercellular adhesion molecule 1 gene and inflammatory bowel disease in Iranian population." (PMID 27099667, 2016). "Variants in ICAM1 have been associated with inflammatory bowel disease." (PMID 31824477, 2019). "Previous research suggests that, while adhesion molecules like ICAM-1 and MAdCAM-1 also contribute to the treatment of inflammatory bowel diseases, selectively blocking VCAM-1 appears to offer higher potential efficacy in managing these conditions." (PMID 38660311, 2024). "The inflammatory bowel disease-promoting roles of ICAM-1 must be considered together with the evidence that ICAM-1 is also potentially involved in a protective or resolving capacity." (PMID 37237555, 2023). "Clinically obtained samples of the chronically inflamed human mesentery of inflammatory bowel disease patients showed ICAM‐1 cell‐to‐cell heterogeneity in small veins." (PMID 36382783, 2023). "Immunostaining of colonic biopsies from patients with inflammatory bowel disease showed intense ICAM-1 staining of the vascular endothelium, which was weaker or absent in controls." (PMID 37237555, 2023). "ICAM-1 was the first candidate to be explored in the field of leukocyte trafficking blockade for inflammatory bowel disease." (PMID 37237555, 2023). "Injection of MSC overexpressing ICAM-1 in mice with an inflammatory bowel disease (IBD) reduced inflammatory damage by promoting their homing to the colon." (PMID 37568164, 2023). "In accordance with such observation, MSCs overexpressing ICAM-1 were shown to possess stronger therapeutic effects than ICAM-1-low MSCs in a mouse model of inflammatory bowel disease." (PMID 32299501, 2020). "Alicaforsen, an ICAM1 anti-sense siRNA, is currently in clinical trials for the treatment of inflammatory bowel disease." (PMID 24086587, 2013). "Supporting this hypothesis, a prior genome-wide association study identified associations between inflammatory bowel disease susceptibility and increased immune activation of specific integrin genes (ITGA4, ITGB8, ITGAL, and ICAM1)." (PMID 39982236, 2025). "Excessive neutrophil accumulation is a histological characteristic of inflammatory bowel disease, however, so therapeutic modulation of ICAM-1 may need to tread a fine line." (PMID 37237555, 2023). "Therefore the decreased expression of ICAM1 by B. breve and B. infantis grown in HMO may aid to reduce the risk of NEC in infants and inflammatory bowel disease in adults." (PMID 26303932, 2015). "The study found that the expression of P-selectin, ICAM1, and VCAM1 was elevated in the inflamed colon tissue of individuals with inflammatory bowel disease." (PMID 37287987, 2023). "The pathogenesis of UC is not currently fully understood by researchers, but among other pathophysiological mechanisms adhesion molecules like the intercellular adhesion molecule 1 (ICAM-1) are supposed to play a crucial role in the inflammatory processes of inflammatory bowel diseases (IBD)." (PMID 33374825, 2020). "For example, MSC-derived ICAM-1 was reported to be critical for the MSC-mediated immunosuppression of T cells, and ICAM-1-modified MSCs remarkably alleviated inflammatory damage in mice with inflammatory bowel disease." (PMID 33692786, 2021). "Given the important role of macrophage efferocytosis in injury resolution and the emerging role of ICAM-1 in macrophage effector function, our group recently examined macrophage ICAM-1 functionality in macrophages in the context of inflammatory bowel disease (IBD)." (PMID 33426539, 2020). "The inflammation and inflammatory bowel disease (IBD) disorders had many commonly modulated genes that were also found in the String analysis that were common with the disorders which included IL-8, ICAM1, RELB, NFκBIA, TNFAIP3, LIF, CXCL1, CXCL2, CXCL3, CXCL10, and TNF-α." (PMID 28099447, 2017).
inflammatory bowel disease (continued). "Interestingly, a recent study in rats reported that the spore-based probiotic, MegasporebioticTM, lowered serum ICAM-1 levels and, to a lesser extent, lowered serum VCAM-1 levels in the context of inflammatory bowel disease (IBD)." (PMID 36771194, 2023).
renal fibrosis (25 papers, 2011 to 2024). A final common manifestation of a wide variety of chronic kidney diseases characterized by glomerulosclerosis and tubulointerstitial fibrosis. "RSV treatment significantly attenuates the damage of renal pathologic changes and inhibition of renal fibrosis, which is associated with down-regulation of macrophage accumulation and the expression of IL-6, ICAM-1 and MCP-1." (PMID 27129290, 2016). "Diabetic mice deficient in MCP-1 and ICAM-1 also show a significant reduction in renal fibrosis with less inflammatory cell infiltration, suggesting that the inhibition of inflammatory cell recruitment may lead to a reduction in extracellular matrix accumulation." (PMID 24027593, 2013). "Renal tubular cells with IS-related injury release transforming growth factor-β or other chemokines such as intercellular adhesion molecule-1, monocyte chemoattractant protein-1, osteopontin, and endothelin-1, which promote renal fibrosis." (PMID 39759603, 2024). "Taken together with the changes in MAPK, NF-κB, and ICAM-1 molecules, it can be inferred that the beneficial effect of sRAGE on renal fibrosis was partly attributed to its inhibitory effect on these MAPK and subsequent inflammatory pathways." (PMID 37261287, 2023). "In the development of DN, the overproduction of FN and ICAM-1 in GMCs leads to the renal fibrosis, therefore reducing ECM accumulation in the kidney can prevent glomerulosclerosis and delay the progression of DN." (PMID 35401165, 2022). "In summary, Icam1 is closely correlated with the occurrence and development of renal fibrosis and is a promising target for CKD." (PMID 36523757, 2022). "Here, we found that Fr inhibited FN and ICAM-1 expression in HG-induced GMCs via affecting ROS generation, therefore preventing renal fibrosis." (PMID 35401165, 2022). "The overproduction of inflammatory cell adhesion molecule (ICAM-1) and the progressive accumulation of extracellular matrix (ECM) such as fibronectin (FN)in GMCs are the main causes of renal fibrosis." (PMID 35401165, 2022). "Upregulated expression of TGFß1 triggered renal fibrosis through the upregulation of extracellular matrix (ECM)-related genes such as ICAM1." (PMID 36363614, 2022). "As observed in animal models of renal fibrosis, several inflammatory mediators, including ICAM-1, are substrate of TIMPs and induce tissue inflammation and damage upon TIMP-1 stimulation." (PMID 36430485, 2022). "Higher expression of ICAM1 attracted inflammatory cells, particularly macrophages, and T-cells which resulted in the over-release of inflammatory cytokines and chemokines resulting in renal fibrosis." (PMID 36363614, 2022). "We have shown that anti-OSM antibody increased the expression of E-cadherin and decreased the expression of α-SMA, suppressed the expression of MCP-1 and ICAM-1, attenuated renal fibrosis, and partially improved 24-hour urinary protein excretion and BUN production." (PMID 28626343, 2017). "In this study, we observed that VCAM-1, ICAM-1, and MCP-1 expression were increased in HG-incubated NRK-52E cells and in experimental diabetic renal injury, which was associated with inflammatory cell infiltration and adhesion, and renal fibrosis." (PMID 24260158, 2013). "Additionally, in a renal fibrosis model, ICAM-1 was upregulated as one of the substrates of TIMP-1." (PMID 36902508, 2023). "Our results indicated that the administration of MA inhibits the expression of pro-inflammatory cytokines and cell adhesion molecules such as IL-1β, TNF-α, MCP-1, and ICAM-1, suggesting that MA may ameliorate renal fibrosis by the inhibition of inflammatory response." (PMID 34588982, 2021). "Second, in-depth molecular experiments, including the investigation of potential role of ICR in regulating ICAM-1 expression, are needed with regard to mechanism of ICR in renal fibrosis." (PMID 35688937, 2022).
renal fibrosis (continued). "The activated NF-κB induce target genes of NF-κB, including ICAM-1 and MCP-1, which in turn enhance inflammation and finally lead to the acceleration of the pathogenesis of glomerulosclerosis and renal fibrosis through ECM accumulation." (PMID 32977573, 2020). "MSCs-derived exosomes suppressed infiltration of dendritic cells into the kidney (by regulating expression of ICAM-1) and inhibited production of the pro-inflammatory cytokines (TNF-α and TGF-β1) and renal fibrosis." (PMID 32082158, 2019). "In our study, JYYS granule significantly attenuates renal pathologic injury and renal fibrosis by downregulating the expression of IL-6, TNF-α, ICAM-1, and MCP-1, which were obviously higher in the SHR group than in WKY rats." (PMID 30598687, 2018). "Although these results suggested that ICAM-1 on RTECs and LFA-1 on leukocytes have some roles in the progression of renal diseases, the pathogenetic roles of their direct interaction in renal fibrosis remain unclear." (PMID 21850266, 2011).
heart failure (24 papers, 2013 to 2025). Inability of the heart to pump blood at an adequate rate to meet tissue metabolic requirements. "The ICAM1 variant rs5491 (p.K56M) is common among Black individuals and has been associated with risk of heart failure with preserved ejection fraction (HFpEF)." (PMID 38074621, 2023). "Other authors showed that the level of nervonic acid is inversely correlated with LDL-C, HDL-C and directly associated with heart failure, cardiovascular risk, cardiovascular and all-cause mortality, markers of inflammation and endothelial activation (hsCRP, IL-6, ICAM-1)." (PMID 36140306, 2022). "Similarly, in a model of pressure overload-induced heart failure, ICAM1-deficient mice have decreased monocyte recruitment and exhibit no overt signs of cardiac fibrosis and minimal ventricular dysfunction." (PMID 29163503, 2017). "In myocardial tissue damaged by γ/δ T cells activation in heart failure, high expression of some molecules associated with γ/δ T cells, including perforin, human leukocyte antigens class I and II, and intercellular adhesion molecule-1, could be found in the myocardium." (PMID 37234159, 2023). "Previous studies have demonstrated that ICAM1 is a key factor mediating pathological cardiac remodeling and heart failure." (PMID 39243097, 2024). "A study on mice with experimentally induced heart failure demonstrated that ICAM-1 regulates cardiac pathological remodeling by mediating left ventricular (LV) leukocyte infiltration, fibrosis, and dysfunction of the heart." (PMID 37568452, 2023). "ROS are implicated in the pathogenesis of various cardiac disorders, including MI and heart failure, and can promote the expression of endothelial adhesion molecules, such as ICAM-1 and VCAM-1, that are critical for neutrophil recruitment." (PMID 35113814, 2022). "As for ICAM1, other studies defined the protein’s crucial role in the development of heart failure by participating in the process of inflammation and apoptosis." (PMID 35370712, 2022). "Meanwhile, ICAM-1 gene is an independent predictor of complications in heart failure patients." (PMID 28623907, 2017). "Moreover, ICAM-1 has been proposed as a therapeutic target in heart failure patients." (PMID 37568452, 2023). "FOXO1 is an important transcription factor, which can promote the promotion of transcription and affect the occurrence and development of heart failure by directly acting on the promoter regions of VCAM1 and intercellular adhesion molecule-1 (ICAM1)." (PMID 35811741, 2022). "Elevated levels of biomarkers involving systemic inflammation, immune function, and ventricular remodeling, including AST, LDH, CRP, CK, HBDH, TNF-α, ET-1, ICAM-1, and MCP-1, also have been related to morbidity and mortality among heart failure patients." (PMID 26269254, 2015). "Moreover, increased expression of ICAM-1 and VCAM-1 was observed in heart failure patients." (PMID 35734399, 2022). "Visfatin increase in type-2 DM patients was related to heart failure and acute coronary syndromes; visfatin appears to mediate vascular endothelial inflammation by inducing the expression of adhesion molecules (VCAM-1 and ICAM-1) and pro-inflammatory cytokines such as IL-1β, IL-6, and TNF-α." (PMID 28590452, 2017).